IGBP1P1 (IGBP1 pseudogene 1)
Synonyms: formerly C14orf19
Gene: Processed pseudogene on chromosome 14 (34,939,324 to 34,940,332, forward strand). Ensembl gene ENSG00000226677.
Diseases named in the same sentence as IGBP1P1 in open-access papers:
IGBP1P1 is named in the same sentence as 1 disease in open-access papers, as found by Europe PMC text mining. Sharing a sentence is not in itself a finding about the gene and the disease. The quoted sentences say what the papers report.
cardiovascular disease (2 papers, 2023 to 2025). "Thus, blocking the ncRNA IGBP1P1 could be a promising strategy to improve cardiac function in cardiovascular disease." (PMID 37491351, 2023).